MAB21L3 (mab-21 like 3)
Synonyms: C1orf161; FLJ38716; D5
Tractability: No criterion of Open Targets' tractability assessment is met for any kind of drug.
Gene: Protein-coding gene on chromosome 1 (116,111,399 to 116,138,149, forward strand). Ensembl gene ENSG00000173212.
Subcellular location (Human Protein Atlas): Nucleoplasm
Gene Ontology:
Molecular function: protein binding
Genetic constraint (gnomAD): Loss-of-function variants: 40 observed, 45.61 expected, observed/expected ratio (o/e) 0.88, 90% interval 0.68 to 1.14. The upper end of that interval is the gene's LOEUF score, 1.14, which puts it in group 5 of 6, group 1 being the genes least tolerant of losing a copy. Missense variants: 430 observed, 467.08 expected, observed/expected ratio (o/e) 0.92, 90% interval 0.85 to 1. Synonymous variants: 186 observed, 186.61 expected, observed/expected ratio (o/e) 1, 90% interval 0.88 to 1.13.
Homologues: Orthologues: chimpanzee MAB21L3 (99% identical), macaque MAB21L3 (95% identical), dog MAB21L3 (84% identical), rabbit MAB21L3 (83% identical), pig MAB21L3 (81% identical), mouse Mab21l3 (77% identical), rat Mab21l3 (77% identical), guinea pig MAB21L3 (75% identical), zebrafish mab21l3 (56% identical), tropical clawed frog mab21l3 (49% identical). Paralogues in human: MAB21L2 (25% identical), MAB21L1 (24% identical), MAB21L4 (22% identical), CGAS (21% identical), ITPRIPL2 (16% identical), ITPRIPL1 (15% identical), ITPRIP (14% identical), MB21D2 (14% identical), TMEM102 (14% identical).
Diseases named in the same sentence as MAB21L3 in open-access papers:
MAB21L3 is named in the same sentence as 16 diseases in open-access papers, as found by Europe PMC text mining. Sharing a sentence is not in itself a finding about the gene and the disease.
MAB21L3 shares sentences with these, for which no sentence is quoted: Hypertension (3 papers); schizophrenia (3); amnesia (1); Anxiety (1); attention deficit-hyperactivity disorder (1); Bethlem myopathy (1); cardiac hypertrophy (1); colitis (1); Dyskinesia (1); gout (1); HIV-1 infection (1); limb-girdle muscular dystrophy (1); melanoma (1); myopia (1); Parkinson disease (1); tumor (1).